SNORD71 (small nucleolar RNA, C/D box 71)
Synonyms: HBII-239; hsa-mir-768; MIRN768
Gene: Small nucleolar RNA gene on chromosome 16 (71,758,402 to 71,758,487, reverse strand). Ensembl gene ENSG00000223224.
Gene Ontology:
Biological process: RNA processing
Cellular component: nucleolus
Homologues: Orthologues: macaque SNORD71 (99% identical), chimpanzee SNORD71 (98% identical), rabbit SNORD71 (91% identical), dog SNORD71 (90% identical), guinea pig SNORD71 (88% identical), pig SNORD71 (88% identical), mouse Snord71 (85% identical), rat Snord71 (83% identical).